ESM1 (endothelial cell specific molecule 1)
Diseases named in the same sentence as ESM1 in open-access papers (continued):
Sharing a sentence is not in itself a finding about the gene and the disease.
tumor (continued). "To further demonstrate the effects of ESM1 and Shikonin on OC growth and VM in vivo, we used OC xenograft tumor models." (PMID 38720298, 2024). "Recently, accumulating reports have demonstrated that ESM1 is overexpressed in various tumor types including lung, prostate, head and neck, kidney, and other cancers." (PMID 39309430, 2024). "In this study, we focused on the mechanism that BCL6 inhibits the tumor infiltrating CD4+T cells through ESM1, however, there are other mechanisms through which BCL6 promotes HCC progression." (PMID 38956432, 2024). "Our findings underscore that ANGPTL4 promotes OC development via JAK signaling and induces angiogenesis in the tumor microenvironment through its interaction with ESM1." (PMID 38212795, 2024). "ESM1 is also an important member of tumor microenvironment and is absorbed by various cells, such as endothelial cells and neutrophils, and promotes immune escape and angiogenesis." (PMID 38720298, 2024). "Our findings show that ESM1 significantly contributes to the proliferation and migration of tumor cells." (PMID 38626010, 2024). "By documenting its overexpression and mechanistic involvement in tumor dynamics, the study provides a foundation for the therapeutic application of ESM1 inhibition." (PMID 38626010, 2024). "It is currently believed that ESM-1 can regulate tumors through tumor-related inflammation, angiogenesis, lymphangiogenesis, and tumor cells themselves." (PMID 38954708, 2024). "Analyzing the relative proportions of each subcluster across the different patient groups revealed that ESM1+EC were enriched in the tumor samples, specifically in obese tumor samples." (PMID 38311726, 2024). "Functionally, ESM1 expression promoted proliferation, anoikis resistance, and motility of GC cells, as well as tumor growth in PDOs and in GC xenograft models." (PMID 39309430, 2024). "The EMT, a critical step in the initiation and promotion of tumor proliferation, migration, and metastasis in GC cells 7, was also crucial for ESM1-modulated progression." (PMID 39309430, 2024). "The results suggested that ESM1 can promote tumor growth, while Shikonin can inhibit the carcinogenic effect of ESM1." (PMID 38720298, 2024). "These molecular functions of ESM1/ANGPTL4 significantly promote angiogenesis in the OC tumor microenvironment." (PMID 38212795, 2024). "Hhex-mediated suppression of ESM-1 is required for normal vascular endothelial function, tumour vasculogenesis, and cancer progression." (PMID 38609535, 2024). "These conclusion suggested the potential benefit of using ESM1 neutralizing antibodies to inhibit tumor immune evasion." (PMID 38956432, 2024). "Immunohistochemical test results showed that Ki-67 protein staining was strong in the tumor tissue of blank control group, while Ki-67 protein staining intensity was significantly decreased in ESM1 interference group." (PMID 38954708, 2024). "The results of wound healing assay manifested that ESM1-mimic group had a significantly smaller width of cell scratch than ESM1-NC group at 24 and 48 h, indicating that the distance of tumor cells migrating to the scratch center rose notably." (PMID 37100467, 2023). "One such molecule is endocan (endothelial cell‐specific molecule‐1 [ESM‐1]), which is indeed a potential immunoinflammatory marker that is related with cardiovascular disease as well as tumor angiogenesis." (PMID 36849916, 2023). "Both tumor types exhibited minimal vascular sprouting and very few ESM1-positive tip cells, cardinal signatures of tumor angiogenesis, at the tumor periphery." (PMID 36828931, 2023). "Evidence indicated that ESM1 was overexpressed in numerous malignancies and involved in neoplasm prognosis." (PMID 37476182, 2023). "The clinical research displayed that the expression level of ESM1 at the tumor site in patients with CRC is correlated with cancer differentiation." (PMID 37100467, 2023).
tumor (continued). "Through the measurement of tumor diameter, it was found that ESM1 can promote the increase of tumor diameter." (PMID 37100467, 2023). "A positive correlation between endocan expression, Knosp grade, and tumor size was confirmed in most studies, although ESM-1 expression was found in tumor or endothelial cells." (PMID 37958702, 2023). "Mechanistically, ESM1 promoted tumor angiogenesis by binding to c-Met on the vascular endothelial cell membrane." (PMID 38201620, 2023). "Combined with results of bioinformatics analysis, the molecular mechanism by which ESM1 promoted tumor angiogenesis in CRC and accelerated tumor progression was explored through suppressing the protein expression of phosphatidylinositol 3-kinase (PI3K)." (PMID 37100467, 2023). "In CRC cells, inhibiting ESM1 expression using siRNA is able to attenuate tumor cell invasiveness, and ESM1-siRNA can restrain tumor metastasis by modulating MMP proteins and EMT-related genes, consistent with findings reported in this study." (PMID 37100467, 2023). "RT-PCR, Western blot and IHC indicated that ESM1 was high expressed in tumor than normal with superior predictive performance of CRC survival." (PMID 36518242, 2022). "This study elucidates why ESM1 is typically elevated in bevacizumab-resistant tumor cells and how it promotes bevacizumab resistance." (PMID 36428773, 2022). "Accumulating studies have implied the correlation of ESM1 with carcinogenesis and tumor progression." (PMID 36522312, 2022). "ESM1 gene expression in various cell lines was inspected by qPCR, which showed that the expression of ESM1 was significantly higher in tumor cells than in normal intestinal epithelial cell line FHC." (PMID 36518242, 2022). "Collectively, these data suggest that ESM1 significantly enhanced tumor invasion in vitro and in vivo and accelerated tumor growth in vivo." (PMID 36428773, 2022). "ESM1 is regarded as a new type of tumor marker, which has been shown to be related to cancer cell proliferation and angiogenesis, and can act as a target as well as regulator of VEGF in endothelial cells." (PMID 36117773, 2022). "After 4 weeks, hematoxylin and eosin (H&E) staining was performed and showed that ESM1 contributed to tumor cell colonization of the lung." (PMID 36428773, 2022). "We further evaluated the expression of DLL4 in ESM1-normal, -high, or -low expression tumor cells and found that DLL4 expression was higher in MDA-MB-231-R/E cells compared to MDA-MB-231-S and shESM1-MDA-MB-231-R cells." (PMID 36428773, 2022). "Taken together, our results demonstrate, for the first time, the expression mechanism of ESM-1, which is upregulated and involved in the tumor progression of RT-R-TNBC cells." (PMID 36077661, 2022). "Our study revealed that tumor-secreted ESM1 played an important role in promoting anti-VEGF resistance." (PMID 36428773, 2022). "Despite being in the theoretical and experimental stages, ESM1 will have infinite prospects in the future as a potential tumor marker for CRC and a novel target for cancer therapy." (PMID 36518242, 2022). "We collected postoperative specimens from a total of 43 CRC patients to determine the expression of ESM1 in CRC tumor tissues." (PMID 36518242, 2022). "Continuous bevacizumab treatment promoted the polarization of M2b macrophages in the TME, resulting in TNFα-induced high ESM1 expression in tumor cells in vivo." (PMID 36428773, 2022). "qPCR results revealed that ESM1 was increased by approximately 9.21− and 2.06-fold in bevacizumab-resistant tumor tissues and cells, respectively, compared to controls." (PMID 36428773, 2022). "ESM1 is highly expressed in tumor tissue compared with adjacent normal tissue and was identified as a hub gene in ESCA." (PMID 35937390, 2022). "In TCGA database of ESCA, compared with 11 normal tissues, ESM1 was highly expressed in 162 tumor tissues (p < 0.001), and ESM1 expression in 11 of 162 tumor tissues was also higher than that in 11 paired adjacent tissues (p < 0.001)." (PMID 35937390, 2022).
tumor (continued). "To ascertain why ESM1 is upregulated in bevacizumab-resistant tumor cells, we evaluated the effects of different concentrations of TNFα on ESM1 mRNA and protein expression in MDA-MB-231-S cells." (PMID 36428773, 2022). "Tumor necrosis in mice receiving bevacizumab combined with ESM1-neutralizing antibodies was significantly higher compared to that in the bevacizumab only group." (PMID 36428773, 2022). "ESM1 is expressed in human vascular endothelial cells, hepatocytes, and renal tubular epithelial cells, and the function of ESM1 is mainly related to the inflammatory response, angiogenesis, and tumor cell growth." (PMID 35937390, 2022). "Retinal vascular outgrowth and filopodia emission were impaired in ESM1KO mice, and overexpression of ESM1 induce tumor formation." (PMID 36428773, 2022). "Given that ESM1 is a secretory proteoglycan, we quantified the protein levels in bevacizumab-resistant and bevacizumab-sensitive cells using dot blot and found that ESM1 expression was higher in bevacizumab-resistant tumor cells." (PMID 36428773, 2022). "The high expression and sustained activation of ESM-1 is prevailing in tumor cells and ESM-1 is recognized as a highly dependent gene for survival." (PMID 34109132, 2021). "Meanwhile, ESM-1 protein in turn plays a role in amplifying the effect of tumor growth factors and inhibiting the migration of effective immune cells into the tumor." (PMID 34109132, 2021). "It is also worth noting that the expression level of ESM-1 is related to tumor aggressiveness and tumor vascularization." (PMID 34109132, 2021). "It is worth noting that ESM-1 is not only intrinsically promoting tumor growth, but also regulating tumor microenvironment." (PMID 34109132, 2021). "The results asserted that inhibition of ESM1 expression impeded the cell proliferation, adhesion between tumor cells and matrix, cell migration, cell invasion, and G2/M-phase transition, while remarkably expedited cell apoptosis of SW13 cells." (PMID 34858850, 2021). "Inhibition of ESM1 distinctly reduced adhesion between tumor cells and matrix and cell invasion in human SW13 cells." (PMID 34858850, 2021). "Given the intimate relationship between ESM-1 and tumor biology, ESM-1 promises to be an CD11a/CD18 active target in cancer therapy." (PMID 34109132, 2021). "Recently, ESM-1 has garnered immense attention owing to its distinctive role in tumorigenesis and tumor progression." (PMID 34109132, 2021). "Blocking ESM-1 with small interfering RNAs (siRNAs) successfully inhibited tumor cell proliferation, migration, invasion, and angiogenesis in diverse cancers." (PMID 34109132, 2021). "As ESM-1 is a kind of proteoglycans which is involved in tumor development, the glycosylation chain is essential for its biological activity." (PMID 34109132, 2021). "RT-qPCR and western blot analysis showed that SNHG14 and ESM1 levels in the tumor group were apparently increased, and miR-211-3p level was obviously decreased in contrast with the normal group (all P < 0.05)." (PMID 33482820, 2021). "Multi-OMICs studies have established largely distinct signaling pathways activated in edge- and core-located tumor cells viz., Esm1/endocan, Bruton’s Tyrosine Kinase, nitrogen metabolism." (PMID 34422657, 2021). "Significantly, ESM-1 can promote cancer progression and metastasis through the regulation of tumor cell proliferation, migration, invasion, and drug resistant." (PMID 34109132, 2021). "As a result, there is a marked reduction of cell numbers, suggesting that down-regulation of ESM-1 can inhibit tumor cells and vascular endothelial cells proliferation." (PMID 34109132, 2021). "Results showed that si-ESM1 inhibits the growth of tumor cells, while si-SLC10A2 promotes the proliferation of tumor cells." (PMID 33330631, 2020).
tumor (continued). "Endothelial cell-specific molecule 1 (ESM1) is secreted by endothelial cells and has been demonstrated to regulate cell adhesion; it can exacerbate inflammatory conditions and enhance tumor proliferation, invasion, and metastasis." (PMID 33330631, 2020). "Another imperative factor in tumor progression is a proteoglycan protein named endothelial cell-specific molecule-1 (ESM-1)." (PMID 33287240, 2020). "The soluble proteoglycan endothelial cell-specific molecule 1 (ESM1) is significantly upregulated in many tumor cells and cirrhosis-related disease." (PMID 32781625, 2020). "Significant differences were observed in the invasion state and maximum tumor diameter between high and low expression of ESM-1 in vascular endothelial tissues (both P < 0.05)." (PMID 31455321, 2019). "Expression levels of these molecules are correlated with those of sphingosine kinase 1 (SPK1), VEGF and endothelial cell-specific molecule 1 (ESM1) in tumor tissues." (PMID 30477236, 2018). "Several tip cell markers, including VEGFR2, endocan/ESM1, and angiopoietin 2, are generally upregulated in tumor vessels and were identified in our analysis of genes associated with vascular abnormality in glioblastoma." (PMID 29763414, 2018). "Endocan, also known as endothelial cell-specific molecule 1, is a secreted proteoglycan that has a single dermatan sulfate side chain attached to serine 137 and demonstrated to be highly elevated on tumour vessels from invasive bladder cancer tissues." (PMID 29207682, 2017). "Over-expressed endothelial-cell-specific molecule-1 (ESM-1) in tumor vascular endothelium contributes to tumor angiogenesis, metastasis, and poor prognosis." (PMID 28514746, 2017). "Conversely, shRNA knockdown of ESM1 in NGFR overexpressing OSCC cells abrogated the tumor growth kinetics and the invasive and metastatic properties associated with NGFR." (PMID 27683113, 2016). "In accordance with these studies, our in vivo and in vitro data both indicate that altered ESM1 expression plays an important role in tumor formation and metastasis of murine oral squamous carcinoma." (PMID 27683113, 2016). "A significant reduction in tumor growth kinetics and tumor volume was observed in the ESM1 knockdown cells." (PMID 27683113, 2016). "In vivo transplantation of ESM1-knockdown cells led to a significant reduction in NGFR-induced tumor growth and pulmonary metastases." (PMID 27683113, 2016). "Consistent with the effect of altered ESM1 expression on migration and invasion of MOC2T cells in vitro, knockdown of ESM1 significantly inhibited tumor growth and reduced the number of lung metastases associated with MOC2T cells in vivo." (PMID 27683113, 2016). "Recently, expression of an intercellular signaling protein present in vascular endothelial cells, termed endocan (endothelial cell-specific molecule-1, ESM-1), was identified to be pivotal for tumor progression and invasion." (PMID 26809958, 2016). "At day 31, the average tumor volume of the control MOC2 cohort was 707.3±78.0 mm3, whereas the average tumor volume of the ESM1 knockdown cohort was 151.6±35.7 mm3." (PMID 27683113, 2016). "The level of endothelial cell specific molecule-1 (ESM-1) mRNA was highly expressed in CSCs, which was aligned with its function in inflammatory responses and tumor progression." (PMID 22606345, 2012). "Endothelial cell-specific molecule 1 (ESM1) plays pivotal roles in tumor angiogenesis." (PMID 40705756, 2025). "Notably, heightened expression of Esm1 is present in retinal endothelial tip cells and in tumor endothelium, establishing it as a valuable marker for neoangiogenesis." (PMID 41214597, 2025). "A deeper investigation into the interaction mechanisms between SERPINH1, PLOD1, ITGA5, and ESM1, and how they collectively influence tumor biological behavior, may reveal potential therapeutic targets for novel treatment strategies." (PMID 40705756, 2025).
tumor (continued). "Finally, we investigated the effect of radiation treatment on survival of tumor-bearing Esm1 WT and KO mice." (PMID 39773984, 2025). "To this end, we treated WT and Esm1 KO mice bearing 7080 tumor cells with ponatinib." (PMID 39773984, 2025). "From both tumor area and liver weight we found that Esm1 overexpression rescued tumor growth." (PMID 38956432, 2024). "Therefore, we further examined the role of the ESM1/ANGPTL4 interaction on the molecular biological behavior of endothelial cells in the OC tumor microenvironment." (PMID 38212795, 2024). "Notably, the tumor growth ability of F014-BL PDOs overexpressing 19del-ESM1 was also significantly lower than that of cells harboring WT-ESM1." (PMID 39309430, 2024). "Then, we used in vivo imaging to monitor tumor growth, and found that Esm1 could partially rescue the phenotype of Bcl6 knockout." (PMID 38956432, 2024). "Therefore, we conducted further evaluations to assess ESM1's role in modulating cell migration and invasion, two fundamental steps of tumor metastasis." (PMID 39309430, 2024). "Moreover, ESM1 was also reported to be a potential marker of the tumor EMT and metastasis in colorectal cancer." (PMID 39309430, 2024). "CAOV3 cells with high levels of ESM1 could induce tumor neovascularization inhibition compared to the NC and vector groups." (PMID 36594088, 2023). "It indicates that ESM1 may have a critical regulatory role in modulating tumor angiogenesis and progression in CSCC by interacting with VEGFα and HIF-1α." (PMID 37476182, 2023). "Consequently, we confirmed through comparison that there is good consistency between our clinical sample dataset and validation set: ESM1 expression was upregulated in tumor samples and significantly correlated with poor prognosis of CSCC patients." (PMID 37476182, 2023). "Human umbilical cord mesenchymal stem cells (hUCMSCs)-derived sEVs-miR-9-3p exert anti-tumor effects by downregulating the tumor promoter gene endothelial cell-specific molecule-1 (ESM-1), leading to reduced BC cell viability, migration, invasion, and enhanced apoptosis." (PMID 37333986, 2023). "We also performed platelet endothelial cell adhesion molecule-1 (CD31, which is often used as a marker for angiogenesis) staining on tumor tissues with high or low ESM1 expression, finding that tumor tissues with a high ESM1 expression had higher CD31 expression." (PMID 38201620, 2023). "Consequently, we provided new insights into the function of ESM1 during tumorigenesis and progression from the perspective of the interaction between tumor cells and endothelial cells." (PMID 38201620, 2023). "We found that tumor volumes and weights were obviously smaller in the ESM1 inhibition group than in the vector group, which indicated that ESM1 could promote the tumorigenicity of OC cells in vivo." (PMID 36594088, 2023). "Notably, the expression of ESM1 was approximately 9.2 times higher in drug-resistant tumor cells than in sensitive cells in vivo." (PMID 36428773, 2022). "The heatmap showed that ESM1 is an upregulated DEG in tumor tissue." (PMID 35937390, 2022). "Their corresponding heatmap showed that ESM1 is an upregulated DEG in tumor tissue." (PMID 35937390, 2022). "Therefore, nucleic acid drugs based on ESM1 silencing in tumor cells are a potential treatment strategy." (PMID 36428773, 2022). "Moreover, ESM1 seems upregulated in many tumor tissues than normal tissues in The Cancer Genome Atlas (TCGA) database." (PMID 36428773, 2022). "ESM1 is an important player in EMT during tumor progression." (PMID 36522312, 2022). "Similarly, Western blot derived from patients’ tumors and paracancerous tissues also showed that ESM1 protein was higher in tumor tissue than in normal tissue." (PMID 36518242, 2022). "From these results, we suggest that nuclear FoxO1 is an important transcription factor that induces ESM-1 expression; however, the increased cytosolic FoxO1 level in tumor cells may be correlated with tumor progression." (PMID 36077661, 2022).